DCHS2 (dachsous cadherin-related 2)
Description:
Calcium-dependent cell-adhesion protein.
Synonyms: CDH27; CDHJ; PCDH23; PCDHJ; FLJ20047; CDHR7
Tractability: Antibody: UniProt predicts a signal peptide or a membrane-spanning region; its Gene Ontology location is reachable by antibodies, with medium confidence; the Human Protein Atlas places it where antibodies can reach. PROTAC: ubiquitination databases record sites on it.
Gene: Protein-coding gene on chromosome 4 (154,231,742 to 154,491,799, reverse strand). Ensembl gene ENSG00000197410.
Subcellular location: Membrane
Subcellular location (Human Protein Atlas): Plasma membrane; Vesicles
Gene Ontology:
Molecular function: protein binding; calcium ion binding
Biological process: axonogenesis; cell-cell adhesion mediated by cadherin; epithelial cell differentiation; cell adhesion; cell differentiation; cell-cell adhesion; epithelium development; establishment or maintenance of cell polarity; heart morphogenesis; homophilic cell-cell adhesion; tissue morphogenesis
Cellular component: adherens junction; plasma membrane; membrane
Genetic constraint (gnomAD): Loss-of-function variants: 137 observed, 173.7 expected, observed/expected ratio (o/e) 0.79, 90% interval 0.69 to 0.91. The upper end of that interval is the gene's LOEUF score, 0.91, which puts it in group 3 of 6, group 1 being the genes least tolerant of losing a copy. Missense variants: 4,053 observed, 4,105.2 expected, observed/expected ratio (o/e) 0.99, 90% interval 0.96 to 1.01. Synonymous variants: 1,648 observed, 1,633.1 expected, observed/expected ratio (o/e) 1.01, 90% interval 0.97 to 1.05.
Homologues: Orthologues: macaque DCHS2 (94% identical), dog DCHS2 (80% identical), chimpanzee DCHS2 (79% identical), rabbit DCHS2 (78% identical), pig DCHS2 (77% identical), mouse Dchs2 (74% identical), rat Dchs2 (74% identical), guinea pig DCHS2 (56% identical). Paralogues in human: DCHS1 (36% identical), CDH23 (24% identical), CDHR2 (8% identical), PCDH7 (8% identical), PCDH1 (7% identical), PCDH9 (7% identical), CDH1 (7% identical), CDH2 (7% identical), PCDH11X (7% identical), PCDH20 (6% identical), CDH4 (6% identical), PCDH11Y (6% identical), and 21 more.
Diseases named in the same sentence as DCHS2 in open-access papers:
DCHS2 is named in the same sentence as 18 diseases in open-access papers, as found by Europe PMC text mining. Sharing a sentence is not in itself a finding about the gene and the disease. The quoted sentences say what the papers report.
colorectal cancer (4 papers, 2022 to 2025). A primary or metastatic malignant neoplasm that affects the colon or rectum. "The frameshift mutation of DCHS2 was reported to be associated with high microsatellite instability in gastric and colorectal cancer." (PMID 36139377, 2022). "Another core mutated gene, DCHS2, which plays an important role in cell adhesion and polarization, was reported as the main molecular feature of high microsatellite unstable gastric cancer and colorectal cancer, which are well-known for their capacity to generate a high TMB." (PMID 41001426, 2025). "In colorectal cancer, DCHS2 expression is significantly elevated compared with adjacent normal tissues, and its abnormal expression is strongly correlated with prolonged progression-free survival." (PMID 40150733, 2025). "DCHS2 may contribute to the occurrence of Alzheimer’s disease and colorectal cancer." (PMID 38584840, 2024).
cardiac hypertrophy (1 paper, 2025). "The data indicate that lncExACT1 and DCHS2 are new regulators of cardiac Yap1, playing a role in exercise-induced cardiac hypertrophy and cardiomyogenesis." (PMID 40463932, 2025). "Consequently, the effects noted on cardiac hypertrophy may be facilitated by Yap1-independent mechanisms downstream of lncExACT1 and DCHS2." (PMID 40463932, 2025).
Cerebro-facio-articular syndrome (1 paper, 2024). "The CDH27/DCHS2 gene, according to the literature, plays a role in facial development, and mutations in it are linked to the Cerebro-facio-articular syndrome of Van Maldergem." (PMID 38699454, 2024).
depression (1 paper, 2024). "Additionally, there was a significantly increased prevalence of heterozygous variants rs1227051-G/A in the CDH23 gene (p = 0.0014, n = 79) and rs12500437-G/T in the DCHS2 gene (p = 0.0390, n = 79) in the “depression” group." (PMID 38699454, 2024).
leukemia (1 paper, 2016). A malignant (clonal) hematologic disorder, involving hematopoietic stem cells and characterized by the presence of primitive or atypical myeloid or lymphoid cells in the bone marrow and the blood. "Through a CGH array analysis, we next extracted five candidate genes (GALNT2, DCHS2, ENTPD8, PNPLA7, FBXW7) involved in drug resistance in leukemia cells." (PMID 28025493, 2016).
oral cancers (1 paper, 2023). "Frameshift deletion of DCHS2 (rs140019361), an STR site that repeats TTTG six times, was found in 95% of oral cancers in elderly individuals, both smokers and nonsmokers." (PMID 37272305, 2023).
schizophrenia (1 paper, 2024). A major psychotic disorder characterized by abnormalities in the perception or expression of reality. "For instance, we discovered that the genetic variants rs1944294-T in the CDH2 gene and rs11935573-G in the DCHS2 gene were significantly more common in the “schizophrenia” group than in the healthy volunteers’ group (p < 0.05)." (PMID 38699454, 2024).
tumor (3 papers, 2021 to 2024). "For instance, fusions of oncogenic proteins TAZ, YAP1, and HIPK2 preserve their tumor-promoting function, while fusions of tumor suppressors, such as NF2, LATS1, FAT1, PTPN14, DCHS2, TAOK1, and TAOK3, results in loss of their function." (PMID 38499647, 2024). "In addition, we performed the expression profiles of significantly mutated genes in one normal group and two tumor groups; we identified 20 DEGs; among them CSMD3, DCHS2, LRP2, RYR2, and ZFHX4 were significantly negatively correlated with PFS." (PMID 35975176, 2022). "In addition, we performed the expression profiles of significantly mutated genes between the normal group and tumor groups and identified 20 differentially expressed genes (DEGs); among them, CSMD3, DCHS2, LRP2, RYR2, and ZFHX4 were significantly negatively correlated with PFS." (PMID 35975176, 2022).
cancer (1 paper, 2023). A tumor composed of atypical neoplastic, often pleomorphic cells that invade other tissues. "Gene enrichment analysis for KEGG revealed two pathways, the Hippo pathway, where DCHS2 was located, and the WNT/calcium pathway, where FAT3 was located, both of which are widely believed to be closely related to cancer." (PMID 37152984, 2023).
DCHS2 also shares sentences with these, for which no sentence is quoted: Alzheimer disease (2 papers); breast carcinoma (1); cervical cancer (1); gastric cancer (1); glioma (1); hair diseases (1); holoprosencephaly (1); lung carcinoma (1); melanoma (1).